XPO1 (exportin 1)
Diseases named in the same sentence as XPO1 in open-access papers (continued):
Sharing a sentence is not in itself a finding about the gene and the disease.
cancer (continued). "CBS9106 binds to the XPO1 reactive site, causing degradation, and its anti-tumor activity has been demonstrated in in vitro in various cancer cell lines and in vivo in xenograft animal models." (PMID 38938904, 2022). "The XPO1 gene plays a role in the control of cell proliferation and affects the loss of control in cancer cell proliferation via various pathways." (PMID 38938904, 2022). "XPO1 overexpression is observed in many types of cancer including DLBCL, and higher levels of XPO1 are associated with poor prognosis in DLBCL and other cancers." (PMID 35159058, 2022). "Exportin-1 is a nuclear transport protein that is overexpressed in cancer cells and associated with inferior outcomes across a range of malignancies." (PMID 34944778, 2021). "Selinexor is an oral selective exportin 1 (XPO1) inhibitor that causes tumor suppression of several cancer models through different mechanisms." (PMID 35582389, 2021). "XPO1 is considered a reasonable target for cancer therapy because overexpressed XPO-1 in cancers causes nuclear mislocalization of tumor suppressors and other regulatory proteins." (PMID 34012430, 2021). "In cancer biology, XPO1 is highly expressed and overactivated in many cancers, causing the improper localization and consequent dysfunction of important tumor suppressors." (PMID 34001144, 2021). "Increased expression of Survivin is also associated with cancer cell survival; specifically, cytoplasmic Survivin is more abundant when XPO1 is overexpressed and promotes chemoresistance through inhibition of apoptosis." (PMID 34944778, 2021). "Selinexor is an FDA approved selective inhibitor of the nuclear export protein exportin-1 (XPO1) and causes specific cancer cell death via nuclear accumulation of tumor suppressor proteins." (PMID 34926302, 2021). "This suggests XPO1 inhibitors are likely to remain effective pharmaceutic candidates for cancer patients with E571 XPO1 mutations." (PMID 33451349, 2021). "In this regard, XPO1 is frequently overexpressed and/or present with recurrent mutations in many cancer types." (PMID 33451349, 2021). "Wide scale genomic analysis across a range of cancer types have discovered the recurrent E571 XPO1 mutations to be particularly enriched in hematologic malignancies." (PMID 33451349, 2021). "XPO1 is frequently overexpressed and/or mutated in human cancers and functions as an oncogenic driver." (PMID 32487143, 2020). "XPO1 is overexpressed in a variety of cancer types, including TNBC, and is associated with poor prognosis in breast cancer." (PMID 33023194, 2020). "SINE compounds can block XPO1-mediated export and can therefore cause mislocalization of tumor suppressors or oncoproteins and decrease the rate of survival of cancer cells." (PMID 31088931, 2019). "Regardless of these links, more work needs to be done to clearly demonstrate the association between the pregnancy hormone and XPO1 expression and nuclear export function enhancement in cancer." (PMID 29735942, 2018). "Elevated expression of XPO1 mRNA and/or protein has been observed in many types of cancer, and high levels of XPO1 expression are associated with poor prognosis in cancer patients." (PMID 30112106, 2018). "Increased XPO1 expression has been linked to poor prognosis in multiple solid and hematologic malignancies, and therefore inhibition of XPO1 is being pursued as a promising target for cancer therapy." (PMID 28810913, 2017). "Expression of XPO1 is up-regulated in several types of cancer and its overexpression is linked to cancer cell survival, proliferation and drug resistance." (PMID 28881784, 2017). "The expression and activity of XPO1 is upregulated in several human cancers and its expression is also linked to the development of chemotherapy resistance." (PMID 25022346, 2014).
cancer (continued). "Together, these studies highlight that XPO1 expression and/or mutation status is correlated with altered immune infiltrates and expression of immune-related genes across multiple cancer types, which may have implications for tumour escape in patients." (PMID 40291981, 2025). "Other potential targets, such as XPO1 may be an attractive pan-cancer target, as it is frequently overexpressed and/or mutated in multiple human cancers and functions as an oncogenic driver." (PMID 38554776, 2024). "This suggests that there may also be non-peptide:HLA class I ligands for KIR2DS2, in addition to the cancer-associated NAPLVHATL peptide derived from XPO1." (PMID 39178254, 2024). "XPO1 mutations, especially the XPO1 E571 mutation, occur in a variety of cancers." (PMID 38783482, 2024). "Data was available for 11,768 individuals in the pan-Cancer cohort, and these showed that high levels of ncr1 expression were associated with an enhanced median survival of 2910 days versus 2089 days, P = 0.017 in individuals with higher levels of XPO1." (PMID 39178254, 2024). "XPO1 is involved in the export of many critical cellular regulators, making XPO1 inhibition a broadly relevant therapeutic strategy, yet the exact mechanisms of action of XPO1 inhibition may be unique to different cancer subtypes and specific mutations." (PMID 38997434, 2024). "XPO1 contributes to normal homeostasis of eukaryotic cells by regulating the export of key proteins, but alterations of XPO1 promote oncogenesis and are associated with decreased survival in cancer." (PMID 36722323, 2023). "Therefore, it was predicted that XPO1 overexpression in malignant tumors causes p62 to move from the nucleus to the cytoplasm, resulting in a change in its subcellular localization." (PMID 37754264, 2023). "The XPO5*rs34324334 variant is thought to be in a highly conserved exportin-1/importin-b-like region and may affect the development of carcinomas." (PMID 37373948, 2023). "Moreover, XPO1 is linked to resistance to various standard-of-care chemotherapies and targeted therapies, which makes it a promising target for novel cancer therapies." (PMID 35573474, 2022). "The mechanistic aspects of XPO1 inhibition using SINE (Selective Inhibitors of Nuclear Export) compounds can affect various processes that are associated with cancer cell proliferation, survival, adhesion, migration, or metastasis, and many of them are downstream of other known targets." (PMID 35091658, 2022). "XPO1 overexpression is nearly universally associated with inferior outcome in cancer." (PMID 34944778, 2021). "Treatment with SINE compounds could impact downstream pathways regulated by XPO1 and have been shown to cause cell cycle arrest, increase in inflammation and apoptosis in cancer cells." (PMID 34584169, 2021). "The nuclear export protein XPO1 is frequently overexpressed in cancers and might be linked with apoptosis resistance." (PMID 34206543, 2021). "Therefore, Mcl-1 downregulation by XPO1 inhibitor was insufficient to induce apoptosis in cancer cells but likely made cancer cells more susceptible to inhibitors targeting of Bcl-2 and/or Bcl-xL." (PMID 31113936, 2019). "Indeed, we found that SINE in vitro and in vivo potentiated the anti-cancer activity of anti-AR agents, enzalutamide and abiraterone, by inhibition of XPO1 and AR splice variants." (PMID 30450161, 2018). "Overexpression of XPO1 has been associated with various forms of cancer and the inhibition of the XPO1-mediated nuclear export by small molecules has been shown to induce apoptosis and abolish cancer growth in in vitro as well as in vivo models of cancer." (PMID 27634897, 2016).
cancer (continued). "Besides cancer, XPO1 function is also associated with impaired immune function during infection." (PMID 40291981, 2025). "Furthermore, dysregulation of transport receptors like CRM1/exportin 1, through overexpression or mutation, can promote the mislocalization of tumor suppressors or oncogenic factors, shifting the balance of critical proteins in favor of cancer progression." (PMID 39459201, 2024). "The numerous cargos transported by XPO1, including many affected by combination treatment and implicated in augmenting selinexor activity, reinforces current understand that no single agent or directed therapy can fully undermine the propensity of a cancer cell to survive." (PMID 34944778, 2021). "In both mutant models, interestingly, a modest increase in sensitivity to SINE inhibition was observed at select doses, suggesting manipulation of molecular signaling pathways stemming from the E571 XPO1 mutation may make these cells more susceptible to this form of anti-cancer treatment." (PMID 33451349, 2021). "As such, selective inhibitors of XPO1 (XPO1i) function have been developed to inhibit cancer cell proliferation and induce apoptosis." (PMID 40291981, 2025). "This highlights the importance of understanding the characteristics of XPO1 inhibition in different cancer models and organs and the short-versus long-term benefits of pro-inflammatory signaling on T cell immune surveillance." (PMID 40291981, 2025). "Reduction of XPO1 protein following SINE treatment was consistent with previous studies in other cancer cell types which have shown that SINE compounds induce a conformational change in XPO1, leading to its recognition and degradation by the proteasome." (PMID 40601866, 2025). "Our results demonstrate that XPO1 inhibition not only disrupts numerous hallmarks of cancer but can also impair the signaling pathway that is the driver of tumorigenesis in FAP." (PMID 40601866, 2025). "Combination regimens incorporating XPO1 inhibitors with other anti-cancer agents have demonstrated synergistic potential across multiple human malignancies." (PMID 40872651, 2025). "Given that HLA-E is heavily influenced by cytokines and other signals, it will be important to dissect the immunogenic properties of XPO1 inhibition in other models of human cancers which recapitulate the TME in patients." (PMID 40291981, 2025). "XPO1 can augment tumourigenesis through virtually all of the hallmarks of cancer, including evasion of immune surveillance." (PMID 40291981, 2025). "XPO1 inhibition impairs numerous hallmarks of cancer, including the ability to induce DNA damage and apoptosis while reducing inflammation, cell proliferation, and angiogenesis." (PMID 40601866, 2025). "Pre-clinical studies have shown that selinexor, an exportin 1 (XPO1) inhibitor, acts as an effective anti-cancer agent and fosters an anti-inflammatory tumor immune microenvironment without harming endogenous tumor-surveillance mechanisms." (PMID 40565816, 2025). "Since drug resistance of traditional chemotherapy has occurred in canine lymphoma case reports, further investigations of drug synergism of XPO1 inhibitor with other anti-cancer drugs are needed." (PMID 40872651, 2025). "Given that XPO1 is frequently overexpressed in manymalignancies, it is plausible that XPO1-mediated nuclear export is co-opted by cancer cellsas a widespread mechanism contributing to oncogenesis." (PMID 41394580, 2025).
cancer (continued). "Due to its role in regulating oncogenes and tumor suppressors, XPO1 has been extensively studied in cancer research." (PMID 41440011, 2025). "In human cancers, promising efficacy has been reported using XPO1 inhibitors in combination with standard chemotherapies, proteasome, or tyrosine kinase inhibitor." (PMID 40872651, 2025). "This review outlines the evidence for the immunomodulatory properties of XPO1 inhibition and discusses the potential for combining and sequencing XPO1i with immunotherapy to improve the treatment of patients with cancer." (PMID 40291981, 2025). "Cancer cells often grow because a protein called Exportin 1 moves important protective proteins out of the cell’s control center (the nucleus), thereby abrogating their function." (PMID 40872651, 2025). "Since XPO1 is the only known cellular target of Selinexor, we previously reported that XPO1 knockdown using siRNA enhanced the replication of MYXV in human cancer cells." (PMID 40007039, 2025). "Despite the growing evidence implicating exportin proteins, particularly XPO1, in cancer biology, their role in ccRCC remains underexplored." (PMID 39882192, 2025). "In the sections below, we review the current literature on the effect of XPO1 inhibition on specific cells of the immune system involved in the anti-cancer response." (PMID 40291981, 2025). "XPO1 has emerged as a promising potential target in cancer therapy because of its consistent involvement in a wide range of tumour types." (PMID 38783482, 2024). "We propose that the up-regulation of XPO1 found in cancer can alter the balance in favor of activation of KIR2DS2-positive NK cells." (PMID 39178254, 2024). "XPO1 is overexpressed in numerous cancer tissues, and its overexpression is accompanied by disease progression, therapeutic resistance and decreased overall survival (OS) or progression‐free survival (PFS)." (PMID 38783482, 2024). "XPO1 inhibition has emerged as a promising therapeutic strategy in the fight against cancer, offering a novel approach to targeting tumorigenic processes and overcoming drug resistance." (PMID 38783482, 2024). "Selinexor is a first class small molecule inhibitor of XPO1, which has shown therapeutic benefits in some adult cancers." (PMID 39594898, 2024). "XPO1 is upregulated in many cancers and is considered an important target in hematologic malignancies, tumor resistance, inflammation, neurodegeneration and viral infections." (PMID 38892287, 2024). "Selinexor, an inhibitor of exportin-1 (XPO-1), effectively promotes nuclear retention and functional activation of tumor suppressor proteins, thereby inducing apoptosis in cancer cells." (PMID 39351358, 2024). "For example, inhibitors of exportin 1 (encoded by XPO1), a nuclear export protein crucial for maintaining cellular homeostasis, have been developed and approved for different cancer conditions." (PMID 39711693, 2024). "Overall, the results of this bioinformatics analysis indicated that XPO1 inhibitor KPT-330 induces changes in critical cancer pathways in CTCL cells." (PMID 38653804, 2024). "While NPCs facilitate selective molecular exchange, misregulation of key transport mediators like XPO1 leads to improper localization of oncogenes and tumor suppressors, further driving cancer progression." (PMID 39459201, 2024). "The targeted disruption of the nuclear‐cytoplasmic transport functionality of XPO1 has led to promising outcomes in cancer therapy." (PMID 38783482, 2024). "We first assessed the expression levels of XPO1 across 85 cancer types through the University of California Santa Cruz Treehouse Childhood Cancer Initiative36." (PMID 38589567, 2024). "Abnormal XPO1 activity allows excessive export of tumor suppressors from the nucleus, rendering them inactive and promoting cancer progression." (PMID 39459201, 2024).
cancer (continued). "The nuclear-to-cytoplasmic transport protein Exportin-1 (XPO1) is an essential regulator for nuclear cargo proteins export, and is associated with poor prognosis in various adult cancers." (PMID 39594898, 2024). "The continuation of the research into XPO1 inhibition extends the potential for developing effective cancer treatments by addressing both nuclear export dysfunction and its wider implications for nucleocytoplasmic transport regulation." (PMID 39459201, 2024). "Prior research indicates that XPO1 inhibitors exert their anticancer effects by inducing apoptosis in cancer cells." (PMID 38653804, 2024). "To identify which other cancers had a positive association between XPO1, ncr1, and survival, we interrogated the 39 different GDC TCGA datasets covering all the cancer types in the TCGA database." (PMID 39178254, 2024). "XPO1 (Exportin-1/CRM1) is a nuclear export protein that is frequently overexpressed in cancer and functions as a driver of oncogenesis." (PMID 39178254, 2024). "Exportin‐1 (XPO1), a crucial protein regulating nuclear‐cytoplasmic transport, is frequently overexpressed in various cancers, driving tumor progression and drug resistance." (PMID 38783482, 2024). "Accumulating evidence suggests a correlation between the aberrant nucleocytoplasmic transport and elevated XPO1 expression in tumours, leading to the occurrence and development of several cancers." (PMID 38783482, 2024). "Disruption of this process can lead to various diseases and research on XPO1 has intensified in recent years, with a focus on the development of new cancer therapies." (PMID 38892287, 2024). "Since selinexor’s approval in MM, there has been increasing interest in using XPO1 inhibition in other cancer context." (PMID 39682167, 2024). "As XPO1 is overexpressed in many different cancers, we used the same methodology to query all the cancer data in the GDC database." (PMID 39178254, 2024). "Previous papers investigating the correlation of XPO1 expression in various cancers with selinexor sensitivity appears to be inconclusive with some reporting a positive correlation and others not finding any." (PMID 39682167, 2024). "Exportin 1 (XPO1), also referred to as chromosomal region maintenance protein 1 (CRM1), is the primary component of this export complex and is overexpressed in many types of cancers." (PMID 37818869, 2023). "Elevated expression of XPO1 enables cancer cells to escape TSPs by exporting them to the cytoplasm where they are unable to function, resulting in dysregulation of growth signalling and increased anti‐apoptotic signalling." (PMID 37601856, 2023). "These proteins play an important role in responding to chemotherapy and radiation, which act by damaging DNA; as such, cancer cells have been found to hijack these processes by XPO1-mediated export of tumour suppressor proteins." (PMID 36671496, 2023). "In most cancer types, selinexor target XPO1 is overexpressed and correlates with poor clinical outcomes." (PMID 37377603, 2023). "XPO1 is overexpressed in various cancers and small inhibitors of nuclear export (SINEs) have been developed to inhibit XPO1." (PMID 36727672, 2023). "XPO1 plays a role in drug resistance, and its inhibitor is currently on the market for cancer treatment." (PMID 37344857, 2023). "On the basis of these previous reports, we tested nuclear export inhibitors that target XPO1//CRM1 to block the nuclear export of proteins in MYXV-infected human cancer cells." (PMID 37377603, 2023). "Although XPO1 is overexpressed in many cancers, only a small number of selective inhibitors of XPO1 have been developed over the years, and few have been clinically validated due to efficacy and safety." (PMID 36980172, 2023).